TRIM3 (tripartite motif containing 3)
Diseases named in the same sentence as TRIM3 in open-access papers (continued):
Sharing a sentence is not in itself a finding about the gene and the disease.
glioma (11 papers, 2009 to 2024). A benign or malignant brain and spinal cord tumor that arises from glial cells (astrocytes, oligodendrocytes, ependymal cells). "Our analysis identifies LOH in 17 cases (24%) of primary human glioma which defines a common 130 kb-wide interval within the TRIM3 locus as a minimal area of loss." (PMID 19250537, 2009). "Our analysis identifies loss of allelic heterozygosity at 11p15.5 in 17 cases of primary human glioma and defines a common 130 kb-wide interval as a minimal area of loss that covers the TRIM3 locus." (PMID 19250537, 2009). "Therefore, TRIM3 was defined as a tumor suppressor and, indeed, TRIM3 loss of heterozygosity is seen in approximately a quarter of human gliomas, correlating with faster tumor growth, whilst in healthy adults it is highly expressed in the cerebellum." (PMID 38115822, 2023). "Interestingly, an early study had reported loss of TRIM3 heterozygosity (LOH) via frequent deletions at 11p15.5 in primary human gliomas." (PMID 36139694, 2022). "Similar to Brat’s, TRIM3’s NHL domain is also required for its growth suppressive properties shown in glioma cells." (PMID 38225354, 2024). "Gene orthology and functional conservation exists between brat and TRIM3, and TRIM3 deletions are observed in 20% of all gliomas (Fig. EV1A)." (PMID 38225354, 2024). "Deletion mapping analysis identified TRIM3 loss in 25% of GBMs and cancer database probing reveals TRIM3 deletions in 24% of grade II–IV gliomas including 20–22% in GBM." (PMID 38225354, 2024). "First, we ascertained TRIM3 downregulation in high (GBM, IDH wild-type) and lower grade (grade II diffuse astrocytoma, DA, IDH mutant) glioma samples, and TRIM3 absence in patient-derived GSCs consistent with literature (Fig. EV1B and C)." (PMID 38225354, 2024). "TRIM3, an NHL- and filamin-domain-containing TRIM protein seems to exert a tumor suppressor role in glioma cells linked to the control of c-MYC, restoration of asymmetric cell division and attenuation of Notch Nuclear Transport." (PMID 36139694, 2022). "On the other hand, deletions of TRIM3 are frequently found in primary human gliomas pointing to a tumor suppressor role for TRIM3." (PMID 30126833, 2018). "Consistent with our results, previous studies also demonstrated that TRIM3 overexpression inhibited glioma cell proliferation and tumor growth." (PMID 28950898, 2017). "LOH within a common minimal 130 kb interval in this region identified the tripartite motif protein 3 (TRIM3) as a candidate tumor suppressor gene involved in glioma progression." (PMID 25953855, 2015). "In contrast to these conventional top-down strategies, we carried out somatic deletion mapping on human glioma DNA focusing on the TRIM3 locus." (PMID 19250537, 2009). "Thus, among the 10 primary human glioma identified with allelic loss at 11p15.5, Q-PCR analysis of ASIII 098 and GBM 157 (20%) indicated homozygous deletions within the TRIM3 gene." (PMID 19250537, 2009). "Besides TRIM3, the β-globin gene cluster resides in the chromosome region 11p15.5, harboring immunity-related genes, such as IGF2, H19, PHLDA2/TSSC3, and SLC22A18, associated with cancers and gliomas." (PMID 36139694, 2022). "We further detect altered genomic dosage of TRIM3 in two glioma cases with LOH at 11p15.5, indicating homozygous deletions of TRIM3." (PMID 19250537, 2009). "Interestingly, genes involved in gliomas development (IGF2, H19, PHLDA2/TSSC3, TRIM3, SLC22A18) are located in the gene locus 11p15.5 of the beta hemoglobin chain." (PMID 32183175, 2020). "In two glioma cases with LOH, altered genomic dosage of TRIM3 indicates homozygous deletions." (PMID 19250537, 2009).
glioma (continued). "Thus, SNP-based allelic retention of short sections within the areas of LOH in primary gliomas ASIII 098, GBM 157, and GBM 164 indicated potential homozygous deletions within the TRIM3 gene." (PMID 19250537, 2009).
breast carcinoma (6 papers, 2020 to 2023). "In this study, we found that TRIM3 and TRIM16 are both down-regulated in breast cancer, and in addition, our results demonstrated that TRIM3 is highly associated with breast cancer grade." (PMID 36180926, 2022). "In the present study, we found that TRIM3 was significantly upregulated in tamoxifen-resistant breast cancer, and was associated with poor survival of patients with breast cancer during tamoxifen therapy." (PMID 34508066, 2021). "Furthermore, the suppressed TRIM3 expression was associated with poor survival rates in breast cancer patients, suggesting that TRIM3 played a role in breast cancer inhibition." (PMID 35066729, 2023). "In our current study, we found that TRIM3, an E3 ligase, can promote ER alpha signaling activity and breast cancer progression." (PMID 35392925, 2022). "Our current study reveals similar conclusions with these two studies, in which TRIM3 is elevated in luminal type of breast cancer and promotes breast cancer progression." (PMID 35392925, 2022). "TRIM3 depletion inhibits breast cancer cell proliferation and migration, while unbiased RNA sequencing data indicated that TRIM3 is required for the activity of estrogen signaling on the -genome-wide scale." (PMID 35392925, 2022). "In the TCGA database, we analyzed TRIM3 expression in each subtype of breast cancer and found that TRIM3 expression was increased in Luminal A, Luminal B and HER2 positive subtypes compared with normal breast tissues." (PMID 35392925, 2022). "Our data demonstrated TRIM3 as a candidate factor in modulating estrogen signaling in breast cancer cells." (PMID 35392925, 2022). "We identified an interesting E3 ligase, TRIM3, that facilitates ER alpha signaling in breast cancer cells." (PMID 35392925, 2022). "TRIM3 can promote breast cancer cell migration and proliferation by stabilizing the ER alpha protein." (PMID 35392925, 2022). "GSEA in Molecular Signatures Database v7.4 showed that the “estrogen response” gene set was enriched in breast cancer cells, suggesting a regulatory effect of TRIM3 on cancer cells in response to ER signaling." (PMID 35392925, 2022). "There are mixed results on the role of TRIM3 in breast cancer, some of which reporting a tumor suppressor role for the enzyme and a few suggesting an oncogenic activity." (PMID 36180926, 2022). "In our study, TRIM3 can facilitate ER alpha signaling, promoting cell proliferation and migration in breast cancer via enhancing ER alpha stability possibly via promoting ER alpha K63-linked poly-ubiquitination." (PMID 35392925, 2022). "As expected, TRIM3 expression was significantly higher in tamoxifen-resistant ER+ breast cancer than that in tamoxifen-sensitive ER+ breast cancer." (PMID 34508066, 2021). "In the present study, we observed that TRIM3 was dramatically overexpressed in breast cancer, which correlated with tamoxifen resistance." (PMID 34508066, 2021). "TRIM3 expression was upregulated in tamoxifen-resistant breast cancer compared with that in tamoxifen-sensitive breast cancer, and was strongly associated with ESR1 SUMOylation." (PMID 34508066, 2021). "Taken together, our results revealed the crucial role of TRIM3 in SUMOylation of ESR1 and the modulation of the tamoxifen response, identifying TRIM3 as a potential target to improve clinical outcomes of breast cancer." (PMID 34508066, 2021). "In the present study, we identified that TRIM3 plays an important role in regulating the ER signaling pathway and confers tamoxifen resistance in breast cancer." (PMID 34508066, 2021). "Consistently, TRIM3 promoted the transcription of ER-targeted genes in tamoxifen-resistant ER+ breast cancer." (PMID 34508066, 2021). "Taken together, these results revealed that TRIM3 responds to tamoxifen resistance and promotes tumorigenicity of breast cancer in vivo." (PMID 34508066, 2021).
breast carcinoma (continued). "In conclusion, our results confirmed that TRIM3 acts as a SUMO E3 ligase to regulate ESR1 SUMO modification and transcriptional activity, thus conferring tamoxifen resistance via the TRIM3/UBC9/ESR1 axis in ER+ breast cancer." (PMID 34508066, 2021). "To further determine the role of TRIM3 in regulating tamoxifen resistance, we detected the expression levels of TRIM3 in 12 ER+ breast cancer cell lines." (PMID 34508066, 2021). "To further examine the effect of catalytic dead mutant of TRIM3 in tamoxifen response in ER+ breast cancer, we constructed TRIM3 mutant (C22A/C25A), which affects its E3 ligase activity." (PMID 34508066, 2021). "The WST-1 assay showed that TRIM3 knocking down inhibited breast cancer cell proliferation, while the EdU staining assay also indicated TRIM3 depletion significantly decreased the cell numbers of EdU incorporation." (PMID 33292295, 2020). "Yet, another two studies reported the TRIM3 played oncogenic roles in breast cancer." (PMID 35392925, 2022). "We further examined the protein localizations of TRIM3 and ER alpha in breast cancer cells." (PMID 35392925, 2022). "Based on these findings, we propose that modulation or inhibition of the TRIM3 protein could be an interesting strategy for ER alpha-positive breast cancer treatment." (PMID 35392925, 2022). "Modulation of TRIM3 expression or function could be an interesting approach for breast cancer treatment." (PMID 35392925, 2022). "In conclusion, our data implicate a nongenomic mechanism by which TRIM3 stabilizes the ER alpha protein to control ER alpha target gene expression linked to breast cancer progression." (PMID 35392925, 2022). "As TRIM3 is a novel modulator of ER alpha signaling, disrupting its protein expression or activity could be a plausible strategy to treat ER alpha-positive breast cancer." (PMID 35392925, 2022). "In addition, in ER+ breast cancer, TRIM3 promotes SUMO modification of estrogen receptor 1(ESR1) and activated the ER signaling pathway." (PMID 36261847, 2022). "We utilized two independent siRNAs to test the effect of TRIM3 on breast cancer cells." (PMID 35392925, 2022). "TRIM3 mRNA showed higher expression in ER+ breast cancer than in ER− breast cancer (p = 1.365E−68)." (PMID 34508066, 2021).
breast carcinoma (continued). "Silencing UBC9 in TRIM3-transduced cells conferred tamoxifen sensitivity in breast cancer." (PMID 34508066, 2021). "Furthermore, TRIM3 overexpression significantly correlated with poor survival of patients with ER+ breast cancer treated with tamoxifen." (PMID 34508066, 2021). "Furthermore, 48 ER+ clinical breast cancer specimens after tamoxifen treatment were used to examine the expression of TRIM3 protein." (PMID 34508066, 2021). "In the present study, we found that TRIM3 was upregulated in tamoxifen-resistant breast cancer tissues compared with that tamoxifen-sensitive breast cancer tissues, and correlated closely with poorer survival in ER+ breast cancer." (PMID 34508066, 2021). "TRIM3 depletion inhibited breast cancer cell proliferation and promoted apoptosis." (PMID 33292295, 2020). "We firstly analyzed the prognostic effect of TRIM3 in breast cancer sample." (PMID 33292295, 2020). "Importantly, TRIM3 overexpression correlated with poor survival of patients with ER+ breast cancer with tamoxifen resistance, identifying TRIM3 as a potential biomarker for the treatment of ER+ breast cancer." (PMID 34508066, 2021). "TRIM3 and TRIM16 genes expression were both positively correlated with the invasion of breast cancer." (PMID 36180926, 2022). "Regarding the roles of TRIM3 and TRIM16 in breast cancer, a limited number of studies have been conducted, most of which are are in vitro." (PMID 36180926, 2022). "In this study, we investigated the expression of TRIM3 and TRIM16 genes in normal and breast cancer tissue samples and compared the expression of the two genes between different clinical and pathological states." (PMID 36180926, 2022). "Taken together, these results suggest that UBC9 is required for TRIM3 regulation of ESR1 SUMOylation and the promotion of tamoxifen resistance in breast cancer." (PMID 34508066, 2021). "Collectively, these results support the view that TRIM3 upregulation promotes ESR1 SUMO modification and ER signaling pathway activity, leading to tamoxifen resistance in ER+ breast cancer." (PMID 34508066, 2021). "Taken together, our results demonstrated that TRIM3 modifies the SUMOylation of ESR1 and confers tamoxifen resistance, which provided a novel therapeutic target for breast cancer therapy." (PMID 34508066, 2021). "However, the correlation between TRIM3 and tamoxifen resistance in breast cancer remains unclear." (PMID 34508066, 2021). "The expression of TRIM3 and TRIM16 are significantly reduced in breast cancer tissues." (PMID 36180926, 2022).
breast carcinoma (continued). "Our study revealed a novel nongenomic regulatory relationship between TRIM3 and ER alpha signaling in breast cancer progression." (PMID 35392925, 2022). "Next, we used six different clinical and pathological parameters, including tumor size, necrosis, histological grade, TNM stage, lymphatic/vascular invasion, and perineural invasion to gain a better view of the effects of TRIM3 and TRIM16 through the progression breast cancer." (PMID 36180926, 2022). "Eventually, we propose TRIM3 and TRIM16 as potential tumor suppressors in terms of breast cancer." (PMID 36180926, 2022). "Hence, we suggest a potential tumor suppressor role for TRIM3 and TRIM16 in breast cancer." (PMID 36180926, 2022). "However, analysis of breast cancer data in the TCGA showed that levels of TRIM3 mRNA and protein did not correlate with levels of ESR1 mRNA and protein." (PMID 34508066, 2021). "In the current study, we found that TRIM3 showed significantly higher expression in recurrent ER+ breast cancer than that in non-recurrent ER+ breast cancer, which consistent with the analysis of TRIM3 expression in response to tamoxifen treatment in ER+ breast cancer data obtained from the TCGA." (PMID 34508066, 2021). "However, the reports regarding TRIM3 in breast cancer are not consistent." (PMID 35392925, 2022). "Furthermore, we found that E2 treatment did not induce ESR1 and TRIM3 expression in breast cancer." (PMID 34508066, 2021). "However, although TRIM3 was shown to function as a tumor suppressor gene in several cancer types, we did not observe any dramatic TRIM3 level change in breast cancer compared with normal breast tissue, which might indicated the uncertain role or dual roles of TRIM3 might exist in breast cancer." (PMID 33292295, 2020).
cervical cancer (6 papers, 2021 to 2024). A primary or metastatic malignant neoplasm involving the cervix. "Research reveals that TRIM3 reduces the population of cervical cancer tumor stem cells and actively participates in regulating their apoptosis and differentiation by engaging various signaling pathways." (PMID 38411731, 2024). "TRIM3 overexpression significantly hinders the migration and invasion capabilities of cervical cancer cells." (PMID 38411731, 2024). "TRIM3 overexpression has a substantial inhibitory effect on the proliferation capacity of cervical cancer cells." (PMID 38411731, 2024). "For instance, miR-454-3p promotes proliferation and induces apoptosis in human cervical cancer cells by targeting TRIM3." (PMID 34016788, 2021). "In cervical cancer, miR-454-3p was found to promote cell proliferation and inhibit apoptosis by targeting tripartite motif-containing 3 (TRIM3)." (PMID 34017681, 2021). "In addition, TRIM3 is a potential target of miRNA (miR)-454-3p to promote the proliferation of human cervical cancer cells and inhibit their apoptosis." (PMID 35066729, 2023). "Furthermore, TRIM3 overexpression exhibits tumor-inhibiting effects in cervical cancer." (PMID 38411731, 2024). "Notably, TRIM3 downregulates the expression of EMT transcription factors, such as Snail, Slug, and TWIST, thus curbing the EMT process in cervical cancer cells and weakening their migration and invasion potentials." (PMID 38411731, 2024).